TNF (tumor necrosis factor)
Diseases named in the same sentence as TNF in open-access papers (continued):
Sharing a sentence is not in itself a finding about the gene and the disease.
diabetes (continued). "We found a significant association between elevated serum TNF-α and poorer performance on the Paired Associates Learning task which was specific to individuals with T2DM in midlife, free from any diabetes-related complications." (PMID 33424582, 2020). "The expression levels of TNF protein are also enhanced in renal glomeruli and tubules of animal models of diabetes." (PMID 32046074, 2020). "Induction of diabetes and/or AFB1 intoxication in the 3rd, 5th, and 7th groups was associated with significantly elevated serum 8-OhdG, IL-1β, IL6, and TNF-α levels, compared to the control group." (PMID 32104544, 2020). "In our study, Cs-A exerted anti-inflammatory and inhibitory effect on retinopathy in the diabetic retina via reducing the retinal levels of IL-1β and TNF-α." (PMID 32019593, 2020). "In the High- and Low-ALS groups, ALS were 4.0 ± 1.2 vs. 1.3 ± 0.7, diabetes prevalence: 14% vs. 4%, CVD risk: 23% vs. 8%, TNF-α levels: 15 ± 9 vs. 11 ± 6 pg/mL, respectively (all p ≤ 0.01)." (PMID 32599711, 2020). "In our study, we found that increased Blautia was positively correlated with inflammatory indicators (IL-1β, TNF-α, IL-6 and LPS) in diabetes." (PMID 32028957, 2020). "The results obtained from the present study revealed that diabetes significantly upregulated mRNA expression levels of TNF-α, NF-кB, and the activity of NF-кB." (PMID 32934245, 2020). "TNF, tumor necrosis factor, which is involved in many diseases including cancer, diabetes, and inflammatory bowel diseases." (PMID 33708105, 2020). "Patients with diabetes are often accompanied by chronic metabolic inflammation, IL-1β, IL-6 and TNF-α and other inflammatory cytokines are upregulated." (PMID 32722636, 2020). "Similar results were observed with the monoclonal antibody infliximab, a TNF-α inhibitor that reduced albuminuria in experimental diabetes." (PMID 32471207, 2020). "Circulating plasma TNFα levels were increased overall by diabetes (P < 0.001) and was increased from 4 weeks of diabetes." (PMID 32153425, 2020). "Insulin, which modulates the production/release of TNF‐a, IL‐1b and P‐selectin in diabetic rats, was also reported to affect pulmonary function and respiratory symptoms in patients with diabetes." (PMID 33145961, 2020). "And the attenuation of the association between the dietary intake of non-α-Toc and TNF-α in established diabetes could suggest that timely intervention for dietary intake of non-α-Toc in the prediabetes stage might be critical for the prevention or delay of diabetes onset." (PMID 32509152, 2020). "In the absence of studies on the effects of different exercise patterns on TNF-α and IL-6 in diabetes, rigorous conclusions cannot be drawn on the effects of different exercise patterns." (PMID 33456672, 2020). "Third, there are few studies on the effects of different types of exercise on TNF-α and IL-6 in diabetes, making it impossible to draw a rigorous conclusion on the effects of different types of exercise." (PMID 33456672, 2020). "From in vivo studies, osthole (20 mg/kg per day for 14 days) reduced the up-regulation of the P2X4 receptor, and downregulated the IL-1β, TNF-α, brain-derived neurotrophic factor, and p-p38MAPK and upregulated IL-10 in diabetes mellitus." (PMID 32028721, 2020). "It is reported that the large blood glucose fluctuation not only increases tumor necrosis factor-α, interleukin-6, and platelet aggregability, but also decreases endothelium dependent vasodilation even before the onset of diabetes." (PMID 32927895, 2020). "Other corroborating evidences are the increased inflammatory markers (NF-κB, TNFα, IL-6, and IL-10) reported in cortical tissues of murine diabetes models, HK2 cell cultures under high glucose environment (NF-κB), and cortical portions of T2D patients (NF-κB)." (PMID 32377524, 2020). "Tumor necrosis factor-α and C-reactive protein levels in the blood serum of patients with chronic pancreatitis and type 2 diabetes mellitus, M±m." (PMID 33456608, 2020).
diabetes (continued). "Thirdly, studies demonstrated that the oxidative stress induced by diabetes increased proinflammatory factors such as the level of TNF-α and IL-6 and raised inflammatory molecules like vascular cell adhesion molecule 1 (VCAM1)." (PMID 33456672, 2020). "Serum adiponectin and TNF-α levels accurately predicted subclinical hyperlipidemia and/or diabetes in an animal model." (PMID 33202729, 2020). "It was, also, stated that the levels of both TNF-α and IL-1β have a direct impact on the initiation and complications of diabetes." (PMID 32626781, 2020). "Eight weeks CS or metformin administration decreased IL-1β, IL-6 and TNF-α levels (CS vs. diabetes, p < 0.01, Met vs. diabetes, p < 0.01)." (PMID 32722636, 2020). "In contrast, approximately 80% of the NOD-HET remained diabetes free, and this was accompanied by reduced iPLA2β (~65%) and TNF-α production by CD4+ T cells and higher M2 marker, Arg1, relative to NOD." (PMID 32814707, 2020). "We have previously shown that diabetes-induced increases in TNFα can increase IRS-1Ser307 phosphorylation in retinal cell types, which results in dysfunctional insulin signal transduction." (PMID 32432228, 2020). "Fourty-two patients with diabetes (80.67%) displayed high concentrations (≥8.1 pg/mL) of TNF- α as compared to controls." (PMID 33202729, 2020). "HCK plays a vital part in the progression of diabetes and does so by activating macrophages and subsequent secretion of TNF-α and inducible NO." (PMID 32684073, 2020). "Fucoidan isolated from Saccharina japonica diminished the toxic effects of diabetes and/or aflatoxin B1 on the liver and kidneys via reducing the blood glucose levels and serum levels of IL-1β, IL-6, and TNF-α." (PMID 33066186, 2020). "TRPV1 and substance P are known to be regulated by NGF and have been related to diabetes-induced neuropathy Mediators of inflammation, particularly the proinflammatory cytokines IL-1β and TNF-α play critical roles in various neuropathic pain conditions." (PMID 32104520, 2020). "IL-6 promotes leukocyte adhesion, microvascular leakage, and TNF-α product in microglial cells in diabetes as these pathological phenotypes were dramatically reduced in the IL-6 knockout mice with diabetes." (PMID 33013692, 2020). "Infliximab, which is a TNF-α antagonist, inhibits sclerostin and RANKL expression in osteocytes and attenuates alveolar bone loss in periodontitis rats with diabetes." (PMID 32708317, 2020). "The increase in these cytokines with diabetes supports previous observations of increases in TNFα, IL-1β, and TGFβ, and concomitant increases in fibrosis and diastolic dysfunction, in mice with diabetes." (PMID 32153425, 2020). "Results indicate that diabetes significantly upregulated the expression levels of miR-146a, miR-9, TNF-α, NF-κB, and subsequently AβPP, BACE1, and Bax." (PMID 32934245, 2020). "Permanent hyperglycemia in diabetes condition leads to increase expression of inflammatory markers like IL-6 and TNF-α as observed in this study." (PMID 33293987, 2020). "In this sense, TNF-α levels in kidneys are increased in experimental animal models of DN and conditional knockout of TNF-α in Mφ revealed a complete block of TNF-α expression in diabetes-induced models." (PMID 32316547, 2020). "Inhibition of TNF-α has considerable therapeutic potential for diseases such as cancer, diabetes, and especially autoimmune diseases." (PMID 33262408, 2020). "TNF-α is one of the most important pro-inflammatory mediators that is critically involved in the pathogenesis of diabetes by inducing tissue-specific inflammation via activation of various pathways such as NF-κB." (PMID 31340612, 2019). "Overweight and obese patients with a diagnosis of type 2 diabetes mellitus show increased blood levels of pro-inflammatory cytokines and markers (e.g. IL-1β, IL-6 and TNF-α)." (PMID 30678702, 2019).
diabetes (continued). "Taken together, these results corroborate the role for the TNF-α/TNFR/NF-κB signaling axis in the progression of diabetes and diabetic kidney injury." (PMID 30868076, 2019). "Z. multiflora extract ameliorated oxidative stress, TNF-α serum level, lipid abnormality, blood glucose, and liver damage in rats with diabetes mellitus." (PMID 30788280, 2019). "The intraperitoneal administration of GNF-2 significantly decreased the diabetes-induced increase in the expression of pro-inflammatory cytokines such as TNF-α and IL-1β mRNAs in the spinal cord tissues." (PMID 31164822, 2019). "In contrast, in patients with diabetes who had poorly controlled blood glucose levels, TNF-α, IFN-γ, IL-2, and IL-1β cytokine levels were increased in response to PPD." (PMID 31815150, 2019). "Our gene expression analysis by RT-qPCR demonstrated that EMP reduced diabetes-induced elevations in the renal expressions of pro-inflammatory cytokine and chemokines TNF-α, MCP-1, CXCL12, and RANTES." (PMID 31168342, 2019). "The seaweed treatment (MESM), after the induction of diabetes, showed that TNF-α was significantly decreased at 200 and 500 mg of seaweed extracts." (PMID 30937278, 2019). "The results of the findings indicate that diabetes mediates testicular damage by increasing the expression of NF-κB which elicit inflammatory cytokine activities, such as those of IL-6, TNF-α, and IL-1β, to promote inflammatory responses." (PMID 31583254, 2019). "Studies conducted in adoptive transfer models have suggested that TNF-α plays a critical role in Th1 and Th2 cells in diabetes induction." (PMID 31049023, 2019). "Diabetes-induced systemic inflammation as evidenced by increased systemic monocyte chemoattractant protein-1 and tumor necrosis factor-α level was decreased by SAR131475." (PMID 30833548, 2019). "Since innate immune activation is a significant characterization of CD and Type 2 Diabetes Mellitus is a well-known disease tied to the activation of immune system, the finding emphasizes the notable role of TNF." (PMID 32099612, 2019). "Mice treated with the P2X7 receptor inhibitor BBG as well as P2X7-/- mice are protected from diabetes-induced upregulation of IL-1β and TNF-α mRNA levels." (PMID 31921199, 2019). "In particular, to better outline the way of action of carotenoids in endothelial dysfunction prevention in diabetes, we pretreated TNF-α-stimulated GD-HUVECs with β-carotene and lycopene." (PMID 30918580, 2019). "Our present study indicates that treatment with fenoldopam attenuates, and doesn’t merely delay, both hyperglycemia and serum TNF levels for over 3 hours after the LPS in endotoxemic mice with diabetes." (PMID 30700738, 2019). "Diabetes increased the retinal levels of TNF and IL-1β, but the treatment with SCH 58261 only slightly attenuated the expression of TNF." (PMID 31748653, 2019). "The result of this study indicated that TNF is key mediator of immune reactions in celiac disease and type 1 diabetes mellitus." (PMID 32099612, 2019). "The hazard ratio (HR, 95% confidence interval) for diabetes was significantly reduced in patients receiving TNF inhibitors, HR 0.35 (0.13, 0.91), compared to patients treated with non-biologic DMARDs other than hydroxychloroquine and methotrexate." (PMID 30673733, 2019). "The findings indicate that the part of immune system that is controlled mainly by TNF is the common feature in CD and diabetes." (PMID 32099612, 2019). "As is well known, diabetes and hypertension lead to inflammation by increasing tumor necrosis factor (TNF)-α, transforming growth factor (TGF)-β, angiotensin II, reactive oxygen species, and hypoxia by induction of nuclear factor-κB (NF-κB) in kidney cells." (PMID 31690042, 2019). "Vitamin D supplementation in patients with diabetes mellitus type 2 helps decrease C-reactive protein and TNF-alpha concentrations, decrease ESR, and increase leptin concentrations." (PMID 30881343, 2019).
diabetes (continued). "Targeted overexpression of TNF-α in the pancreatic islets of transgenic NOD mice accelerated the progression of diabetes." (PMID 31049023, 2019). "The expression of TNF-α and IL-1β mRNAs in the lumbar segment of the spinal cord of mice with diabetes was significantly increased 2 weeks after STZ injection." (PMID 31164822, 2019). "The depletion of MDMs by clodronate liposomes alleviated diabetes-induced tactile allodynia (P < 0.05) and reduced the infiltration of MDMs (P < 0.001) as well as the expression of IL-1β and TNF-α in the spinal cord (P < 0.05)." (PMID 31534976, 2019). "NON-RATT021972 siRNA treatment suppressed the up-regulated expression and activation of the P2 × 3 receptor and reduced the hyperalgesia potentiated by the pro-inflammatory cytokine TNF-α in Type 2 diabetes mellitus rats." (PMID 31680832, 2019). "The healing properties of NT have been confirmed in a murine model of diabetes, where collagen matrices, loaded with NT-enhanced wound healing, decreased the expression of TNF-α and IL-1β and reduced the infiltration of inflammatory cells into the wound." (PMID 31614422, 2019). "In the present study, induction of diabetes increased (p < 0.05) levels of proinflammatory cytokines TNF-a, IL-1b and IL-6 in rats." (PMID 31412679, 2019). "In the current study, the expression of CYP51A1 was inhibited, which will cause the upregulation of the NF-κB signaling pathway, leading to the upregulation of TNF-α, which will then trigger an inflammatory reaction and aggravate the symptoms of diabetes." (PMID 30131712, 2018). "Results exhibited that higher mRNA levels of CRP, IL-6, IL-1β, and TNF-α in diabetes rats were obviously reduced after the treatment with STX for 7 weeks." (PMID 30210342, 2018). "Oral administration of different strawberry extracts down-regulated the expression of TNF-α in nicotinamide–streptozotocin-induced diabetes in rats." (PMID 30291211, 2018). "HIV, diabetes, history of smoking, taking a TNF-α inhibitor and on transplant immunosuppression were more common in US born subjects compared to immigrants." (PMID 30440033, 2018). "In particular, this diabetes-induced inflammation is grossly apparent in the retina based on the levels of proinflammatory cytokines, such as tumor necrosis factor-alpha (TNFα), interleukin- (IL-) 1-beta (IL-1β), VEGF, IL-8, and IL-6." (PMID 29682582, 2018). "Fas and IFNγ have been reported to be more important in killing pancreatic beta cells in T-cell dependent murine models of diabetes mellitus although TNFα assistance was essential, as was also confirmed in this model." (PMID 29464051, 2018). "Enhanced expression of AGEs in diabetes not only provokes NF-κB activation, but also leads to an subsequent increase in IL-6 and TNF-α release, which further exacerbates bone resorption." (PMID 30459613, 2018). "TNF-α mediates metabolic changes and increased TNF-α was found in type 2 diabetes mellitus and was associated with lower muscle mass and strength in older groups." (PMID 29686666, 2018). "Both diabetes and periodontal disease involve elevated levels of inflammatory mediators such as interleukin-1β (IL-1β); tumour necrosis factor-α (TNFα), accumulation of reactive oxygen species (ROS) and advanced glycation end products (AGEs)." (PMID 30405072, 2018). "Our results revealed that HSP60 levels were attenuated in lean subjects with diabetes along with increased expression of the inflammatory markers IL-6 and TNF-α, as observed in our obese subjects." (PMID 29467719, 2018). "The immune response to the proinsulin-2 peptides escalated from a mild Th1/Th17 response 1 week post prime to an abundant production of IFN-γ, IL-6 and TNF-α in particular by week 7, the time of earliest diabetes onset." (PMID 30237494, 2018). "In close relationship with the effect on NF-κB, citicoline was able to ameliorate the perivascular overexpression of TNF-α induced by diabetes." (PMID 30127248, 2018).
diabetes (continued). "In neonatal NOD mice, treatment with TNF promoted the development of diabetes accompanied with a reduced number and impaired function of Tregs instead." (PMID 29725328, 2018). "Increased levels of cytokines, including IL-1β, IL-6, IL-8, VEGF and TNFα have been found in diabetic patients and rodent models of diabetes." (PMID 29301251, 2018). "Epidemiological evidence suggests that inflammatory markers, such as TNF-α and IL-6, predict the development of diabetes and glucose disorders." (PMID 30914847, 2018). "One is leukocytes adhere to retinal vascular endothelium that occurs very early after the onset of diabetes, which subsequently triggers release of pro-inflammatory cytokines such as tumor necrosis factor-α (TNFα) and interleukins (ILs)." (PMID 29513760, 2018). "The CS-ZPV-treated groups at doses 1 and 2 had lower levels of IL-1β and TNF-α cytokines at 7 and 14 days than those the untreated diabetes group." (PMID 30670966, 2018). "By contrast, administration of TNF to young adult NOD mice also ameliorated diabetes but enhanced the proliferation of Tregs instead." (PMID 29725328, 2018). "In conclusion, α-LA strikingly ameliorates steatosis in this animal model of diabetes fed with HFD by decrementing the inflammatory marker TNF-α and reducing oxidative stress." (PMID 30208622, 2018). "The main mechanism implicated in these beneficial effects were the inhibition of the downregulation of synaptophysin and its anti-inflammatory properties by means of preventing the upregulation of NF-κB and TNF-α (Tumor Necrosis Factor α) induced by diabetes." (PMID 30127248, 2018). "This is in line with a recent report describing the deficient production of TNF-α, IL-6, and MCP-1 in response to different Mycobacterium species by MFs isolated from mice with diabetes." (PMID 29513874, 2018). "The effect toward better control of diabetes is consistent with the decrease in TNF-α level observed in the diacerein group at the end of the trial." (PMID 29805981, 2018). "We recently developed conditions for culturing podocytes which mimic those experienced by podocytes during diabetes, an environment rich in glucose, insulin and inflammatory cytokines, TNFα and IL-6, which promotes insulin resistance." (PMID 29500363, 2018). "Subjects on TNFα blockers had less diabetes (6% vs. 26%), smoking >1 pack per day (6% vs. 11%), and renal failure (0% vs. 6%) compared to the control group." (PMID 30440033, 2018). "Given that diabetes worsens systemic inflammation due to higher TNF production in the spleen, we analyzed the effects of diabetes at the cellular level in primary culture of splenocytes." (PMID 29780390, 2018). "Early inflammatory events in diabetes triggers the release of pro-inflammatory cytokines including TNF-α, IL-1β, and IL-6, which gradually increase as the disease progresses." (PMID 30443223, 2018). "Induction of diabetes in rats using streptozotocin increased retinal IL-6 and TNFα, whereas anti-inflammatory IL-10 was decreased, suggesting a pro-inflammatory and neurotoxic shift." (PMID 29301251, 2018). "Our results show that diabetes exacerbates the inflammatory responses to bacterial endotoxin by increasing TNF production in the spleen." (PMID 29780390, 2018). "Animal models with type 2 diabetes mellitus suggest that TNF-α plays an essential role in prolonging periodontal inflammation and in the development of insulin resistance." (PMID 30356347, 2018). "We previously demonstrated that increased levels of proNGF protein lead to increased inflammatory cytokines α2M and TNFα in diabetes." (PMID 29927948, 2018). "This study aimed to investigate the association of plasma TNF-α, IL-6, and lL-10 levels and cytokine gene polymorphisms [TNF-α (-308 G→A), IL-6 (-174 C→G) and IL-10 (-1082 A→G, -819 T→C and -592 A→C)] in type 2 diabetes mellitus (T2DM) and obese patients." (PMID 28225860, 2017).